RNU5A-1 (RNA, U5A small nuclear 1)
Synonyms: U5A; U5B1; RNU5; RNU5A; RNU5C
Gene: Small nuclear RNA gene on chromosome 15 (65,296,051 to 65,296,167, forward strand). Ensembl gene ENSG00000199568.
Pathways (Reactome):
Gene expression (Transcription): RNA polymerase II transcribes snRNA genes
Gene Ontology:
Biological process: formation of quadruple SL/U4/U5/U6 snRNP; spliceosomal tri-snRNP complex assembly
Cellular component: U4/U6 x U5 tri-snRNP complex; U5 snRNP
Diseases named in the same sentence as RNU5A-1 in open-access papers:
RNU5A-1 is named in the same sentence as 2 diseases in open-access papers, as found by Europe PMC text mining. Sharing a sentence is not in itself a finding about the gene and the disease.
RNU5A-1 shares sentences with these, for which no sentence is quoted: colon cancer (1 paper); tumor (1).